COL2A1 (collagen type II alpha 1 chain)
Diseases named in the same sentence as COL2A1 in open-access papers (continued):
Sharing a sentence is not in itself a finding about the gene and the disease.
congenital toxoplasmosis (2 papers, 2008 to 2017). Toxoplasma infection that is present from birth. "Logistic regression analysis for genotype-wise associations between ABCA4 and COL2A1 and risk of congenital toxoplasmosis in the EMSCOT mother-child pairs." (PMID 18523590, 2008). "FBAT analysis under dominant model of inheritance for associations between ABCA4 and COL2A1 and congenital toxoplasmosis in the NCCCTS child-parent trios." (PMID 18523590, 2008). "Overall, our finding that polymorphisms at ABCA4 and COL2A1 are associated with ocular and other manifestations of congenital toxoplasmosis provides novel insight into the molecular pathways that can be affected by congenital infection with this parasite." (PMID 18523590, 2008). "Herein we examined the specific genetic hypothesis that polymorphisms in two genes known to be associated with ocular disease, ABCA4 and COL2A1, are associated with ocular disease caused by congenital toxoplasmosis." (PMID 18523590, 2008). "These associations between clinical outcomes of congenital toxoplasmosis and polymorphisms at ABCA4 and COL2A1 provide novel insight into the molecular pathways that can be affected by congenital infection with this parasite." (PMID 18523590, 2008). "Using these cohorts we show that ocular and brain disease in congenital toxoplasmosis associate with polymorphisms in ABCA4, while polymorphisms at COL2A1 encoding type II collagen associate only with ocular disease." (PMID 18523590, 2008). "This has important implications in relation to the lack of skeletal features in clinical phenotypes observed in congenital toxoplasmosis in relation to the epigenetic silencing of the maternally-derived allele that we have observed for the type IIB isoform of COL2A1." (PMID 18523590, 2008).
diabetic (2 papers, 2024). "Upstream regulator analysis suggested COMMD1, HIF1A, EGLN, PIK3R1 and MTORC1 as major upstream regulators for the phase shifts, while HSP90B1, YWHAZ, CNGA3, COL2A1 and TFRC were identified as the major upstream regulators for the amplitude changes observed in the diabetic retina." (PMID 38039846, 2024).
Hepatic fibrosis (2 papers, 2024 to 2025). The presence of excessive fibrous connective tissue in the liver. "Moreover, the mRNA expression levels of asma, Tgfβ, Col2a1, and Col5a1 were increased in the liver of SD mice, suggesting an increased tendency to liver fibrosis." (PMID 38633246, 2024).
idiopathic scoliosis (2 papers, 2020 to 2023). A scoliosis with no known cause. "The results of immunohistochemistry confirmed the degeneration of IVD by showing a reduced expression of Aggrecan and Col2A1 in degenerated IVD compared to that of the idiopathic scoliosis group." (PMID 37667246, 2023).
metastatic tumor (2 papers, 2021 to 2025). "Expression of COL2A1, COL11A1, COL6A1, COL6A2 and LUM tended to be higher in primary/metastatic tumor than in normal tissue." (PMID 40927672, 2025).
osteochondrodysplasia (2 papers, 2018 to 2025). A term referring to disorders characterized by abnormalities in the development of bones and cartilage. "Similarly, autosomal dominant mutations in COL2A1 are responsible for a number of osteochondrodysplasias, and mutations in both COL2A1 and TRIP11 are implicated in Type 2 and Type 1A achondrogenesis, respectively." (PMID 29567674, 2018).
Acetabular dysplasia (1 paper, 2024). A smaller than normal acetabulum that has insufficient femoral head coverage leading to abnormal hip joint contact pressures, instability and pain. "This study provides new evidence linking COL2A1 gene mutations to acetabular dysplasia with SC, demonstrating that NGS can enhance diagnostic precision." (PMID 39902299, 2024). "The presence of acetabular dysplasia in these patients expands the phenotypic spectrum of COL2A1 mutations." (PMID 39902299, 2024). "To date, COL2A1 gene mutations have not been reported in cases of acetabular dysplasia with SC." (PMID 39902299, 2024).
Apert syndrome (1 paper, 2021). Apert syndrome (AS) is a frequent form of acrocephalosyndactyly, a group of inherited congenital malformation disorders, characterized by craniosynostosis, midface hypoplasia, and finger and toe anomalies and/or syndactyly.
astrocytoma (1 paper, 2025). "Among the 19 collagen gene transcripts that were profiled, COL16A1, COL8A1, and COL2A1 exhibited higher levels in the GBM tissue versus the grade III astrocytoma sample." (PMID 41366031, 2025).
autism (1 paper, 2023). Persistent deficits in social interaction and communication and interaction as well as a markedly restricted repertoire of activity and interest as well as repetitive patterns of behavior. "One individual in the third generation was biallelic heterozygous for both COL2A1 mutations and showed ocular and joint findings in addition to autism and severe developmental delay." (PMID 37107605, 2023).
autosomal recessive Stickler syndrome (1 paper, 2021). "A loss-of-function mutation in COL2A1 and COL9A2 identified as a causative locus in autosomal recessive Stickler syndrome characterized by orofacial and auditory abnormalities." (PMID 34639189, 2021).
cardiac hypertrophy (1 paper, 2013). "Reactive oxygen species (ROS) have been shown to up-regulate expression of profibrotic genes, such as col2a1, col1a1, and fn1, thereby resulting in direct extracellular matrix deposition in a transgenic mouse model, and resulting in cardiac hypertrophy." (PMID 23922799, 2013).
cartilaginous tumors (1 paper, 2020). "Some studies have reported that the COL2A1 mutation in high-grade cartilaginous tumors is significantly higher than that in low-grade cartilaginous tumors." (PMID 33585230, 2020).
chondroblastic osteosarcoma (1 paper, 2011). An osteosarcoma characterized by the presence of atypical cartilage of variable cellularity. "The genes that make up the chondroblastic-specific part of this expression profile are mostly chondroid matrix-associated genes, such as ACAN, COL2A1, and MATN4, and are all upregulated in chondroblastic osteosarcoma." (PMID 21933437, 2011).
dolichostenomelia (1 paper, 2022). "We report here for the first time that COL2A1 variants are associated with a MASS-like phenotype characterized by tall stature, arachnodactyly, spine deformity, dolichostenomelia, foot deformity, arched palate, and pectus deformity." (PMID 35296718, 2022).
Ehlers-Danlos syndrome (1 paper, 2024). The Ehlers–Danlos syndromes (EDS) are a clinically and genetically heterogeneous group of heritable connective tissue disorders (HCTDs) characterized by joint hypermobility, skin hyperextensibility, and tissue fragility. "An Ehlers-Danlos syndrome of the vascular type was documented in one patient with a missense variant in the COL2A1 gene." (PMID 38256594, 2024).
embryonal carcinoma (1 paper, 2013). A non-seminomatous malignant germ cell tumor characterized by the presence of large germ cells with abundant cytoplasm resembling epithelial cells, geographic necrosis, high mitotic activity, and pseudoglandular and pseudopapillary structures formation. "In the murine embryonal carcinoma-derived cell line ATDC5, TrkB inhibition with either K252a or AG879 dramatically blocks chondrocyte differentiation as measured by Col2a1 and ColX expression, but does not alter IGF-I-stimulated proliferation." (PMID 23776632, 2013).
epilepsy (1 paper, 2021). A brain disorder characterized by episodes of abnormally increased neuronal discharge resulting in transient episodes of sensory or motor neurological dysfunction, or psychic dysfunction. "There was heterogeneity regarding causative genes (n = 754) with some of the most common ones being COL2A1 (n = 12; skeletal dysplasia), SCN1A (n = 8; epilepsy), and TNFRSF13B (n = 4; inborn errors of immunity)." (PMID 33726816, 2021).
fetal hydrops (1 paper, 2025). "Increased NT or fetal hydrops was observed in 13/36 (36.1%) cases, including two cases of skeletal dysplasia (due to COL2A1 and ACAN variants) and two cases of spondylocostal dysostosis." (PMID 39674903, 2025).
fibrosis (1 paper, 2025). the formation of excess fibrous connective tissue in an organ or tissue in a reparative or reactive process. "The results revealed that COL1A1 expression was significantly upregulated, while COL2A1 expression was downregulated in the Model group compared to the Blank control group, indicating that puncture-induced modeling increased disc fibrosis and impaired NP functionality." (PMID 40356987, 2025).
gastric tumors (1 paper, 2022). "The components of the hub were all upregulated genes in gastric tumors, except for COL2A1 (collagen type II alpha 1 chain)." (PMID 35739492, 2022).
hip osteoarthritis (1 paper, 2025). "The p.Gly1170Ser mutation in COL2A1 leads to significant structural changes in joint cartilage, resulting in early-onset hip osteoarthritis, avascular necrosis of the femoral head, or LCPD." (PMID 40041162, 2025).
Hyperglycemia (1 paper, 2021). An increased concentration of glucose in the blood. "Moreover, the top interacting genes are PTGS2, the function of which has been found to be related to hyperglycemia, and COL2A1, the expression of which is related to inflammation." (PMID 33505497, 2021).
hypophosphatemia (1 paper, 2023). Lower than normal levels of phosphates in the circulating blood. "Two third-generation siblings with skeletal dysplasia and hypophosphatemia harbored both COL2A1 and PHEX pathogenic variants which co-segregated with phenotypes across the paternal and maternal pedigrees." (PMID 37278761, 2023). "However, the COL2A1 variant was not responsible for the hypophosphatemia of the two siblings, and their mother also suffered from hypophosphatemia." (PMID 37278761, 2023).
infantile epileptic encephalopathy (1 paper, 2024). an epileptic condition characterized by epileptiform abnormalities associated with progressive cerebral dysfunction. "Pathogenic COL2A1 variants have been associated with varying skeletal dysplasias, including achondrogenesis and hypochondrogenesis (OMIM 200610), while pathogenic PCDH19 variants have been associated with a female-restricted form of sporadic infantile epileptic encephalopathy (OMIM 300088)." (PMID 40225944, 2024).
knee osteoarthritis (1 paper, 2017). "Western blots were evaluated for differences in MMP-13, TIMP-1, NF-κB, IκB-β, and COL2A1 protein expression among the groups of rats with MIA-induced knee osteoarthritis." (PMID 28594958, 2017).
lentivirus infection (1 paper, 2021). Virus diseases caused by the Lentivirus genus. "Immunofluorescence experiments further revealed that OA progression, as assessed primarily by MMP13, ADAMTS4, and COL2A1, was inhibited in HCs following circRSU1 shRNA lentivirus infection." (PMID 33408787, 2021).
lipoma (1 paper, 2015). A benign, usually painless, well-circumscribed lipomatous tumor composed of adipose tissue. "Pten deletion in the cartilage and perichondrium mesenchymal lineages of Col2a1-cre transgenic mice also displayed increased marrow adipocytes and lipoma formation." (PMID 26317218, 2015).
malocclusion (1 paper, 2015). "In addition, Col2a1–Cre; Npr2flox/flox mice also exhibited malocclusion just as observed in systemic or cartilage-specific CNP knockout mice." (PMID 26014585, 2015). "A considerable proportion of total CNP knockout mice exhibit severe malocclusion, which may prevent normal eating; Col2a1–Cre; Nppcflox/flox mice also exhibit this phenotype." (PMID 26014585, 2015).
meningioma (1 paper, 2022). A generally slow growing tumor attached to the dura mater. "We found that the expression of COL2A1, and COL9A3 were significantly upregulated in meningioma tissues, and the expression of COL14A1, COL4A3, and COL4A2 was significantly down-regulated." (PMID 36538194, 2022).
mesenchymal tumors (1 paper, 2010). "Five genes were significantly differentially expressed in chordoma tumors compared with three control groups (nonchordoma mesenchymal tumors, normal tissues, and IVD): T, CD24, COL2A1, CA3, and KRT19." (PMID 21253487, 2010).
necrosis (1 paper, 2025). The phenotypic observation that death has occurred in groups of cells or in one or more tissues due to external factors, such as infection, toxins, mechanical trauma, loss of blood supply and other injuries (e.g. corrosion or burning). "They found that familial femoral head necrosis is dominantly inherited and identified a gene mutation in the 12q13 region, with further sequencing of the COL2A1 gene exon encoding collagenase II confirming a mutation at codon 1170." (PMID 40041162, 2025). "LCPD is idiopathic ischemic necrosis of the femoral head in children, and other scholars have also reported the same COL2A1 gene locus mutations in familial LCPD patients." (PMID 40041162, 2025).
osteonecrosis (1 paper, 2022). A none disease characterized by death of bone tissue due to a lack of blood supply. "It has also been suggested that COL2A1, involved in osteonecrosis of the femoral head, is related to skeletal dysplasia due to failed cartilage development and growth." (PMID 35264229, 2022).
prostate carcinoma (1 paper, 2022). A carcinoma that arises from epithelial cells of the prostate gland. "COL2A1 was found to be associated with rheumatoid arthritis and with prostate carcinoma in previous GWAS." (PMID 35624665, 2022).
ptosis (1 paper, 2016). The drooping of the upper eyelid. "Herein we report an Indian boy with STL1 demonstrating c.2710C>T mutation in COL2A1 gene with short stature, ptosis, and uveitis, hitherto unreported in published literature." (PMID 28018693, 2016).
pulmonary hypertension (1 paper, 2019). Increased pressure within the pulmonary circulation due to lung or heart disorder. "Functionally, Col2a1 has been reported to be involved in the arterial tortuosity syndrome, which is often associated with PA stenosis and pulmonary hypertension." (PMID 31331330, 2019).
Respiratory distress (1 paper, 2015). Respiratory distress is objectively observable as the physical or emotional consequences from the experience of dyspnea. "Targeted inactivation of the COL2A1 gene resulted in the closure of the alveoli of the lungs and mutant mice died of acute respiratory distress." (PMID 26307084, 2015).
Retinal dystrophy (1 paper, 2022). Retinal dystrophy is an abnormality of the retina associated with a hereditary process. "Ten families had variants in genes related to a syndromic disease with retinal dystrophy (COL9A1, CEP290, PCDH15, LRP5, PEX1, CFH, COL2A1 and COL11A1)." (PMID 35457050, 2022).
rhegmatogenous retinal detachment (1 paper, 2022). Retinal detachment secondary to retinal tear or break. "A family with this condition was also found to have a pathogenic variant in COL2A1 p.(Gly318Arg), and the same gene has also been found to have a weak association with an increased risk of rhegmatogenous retinal detachment in the general population." (PMID 35741851, 2022).
short-limbed dwarfism (1 paper, 2024). "Heterozygous mutations in the COL2A1 have been proven to cause a lethal perinatal form of short-limbed dwarfism in humans." (PMID 39092175, 2024).
silicosis (1 paper, 2021). Silicosis is a respiratory disease caused by breathing in (inhaling) silica dust. "For example, Plerixafor inhibits the CXCR4 chemokine receptor, which is induced in silicosis; Retinoic acid may both inhibit the expression of COL2A1 and activate MUC5AC." (PMID 34149803, 2021).
spondylometaphyseal dysplasia (1 paper, 2023). Spondylometaphyseal dysplasias are a heterogeneous group of disorders associated with walking and growth disturbances that become evident during the second year of life. "A heterozygous c.2833G > A(p.G945S) missense variant in the COL2A1 gene, which is known to be responsible for SED or Spondylometaphyseal dysplasia (SMED), was found in the proband, and his father and brother." (PMID 37278761, 2023).
Stillbirth (1 paper, 2025). Death of the fetus in utero after at least 22 weeks of gestation. "A study on exome sequencing found that missense mutations of COL2A1, PEIZO1, and HNF1B were associated with stillbirth, and ultra-rare variants in PTPN11, SMC3, and FBN2 were known to cause stillbirth." (PMID 39906474, 2025).
synthesis (1 paper, 2024). "This is, to our knowledge, the largest amount of patient data used for this type of study, which suggests that there is no strong correlation between Perthes and COL2A1-related collagen synthesis disorders." (PMID 38195509, 2024).
Talipes equinovarus (1 paper, 2014). Talipes equinovarus (also called clubfoot) typically has four main components: inversion and adduction of the forefoot; inversion of the heel and hindfoot; equinus (limitation of extension) of the ankle and subtalar joint; and internal rotation of the leg. "In F20, a male fetus with increased nuchal translucency (>3.5 mm), tricuspid regurgitation and abnormal legs and feet with an extended posture and bilateral talipes equinovarus anomaly, we found c.3490G>T (p.1164G>C) in COL2A1 (MIM 120140, ENST00000380518)." (PMID 24476948, 2014).
thrombophilia (1 paper, 2025). A condition characterized by an abnormally high level of thrombi. "For example, COL2A1 mutations weaken the strength of the epiphyseal cartilage matrix, mutations in Factor V Leiden, and deficiencies in Protein-C and Protein-S contribute to thrombophilia, while nitric oxide synthase and IL-6 gene polymorphisms potentially affect endothelial cell function." (PMID 40041162, 2025).